DNAAF8 (dynein axonemal assembly factor 8)
Description:
In cyliated cells, dynein axonemal particle-specific protein required for deployment of ODA to the axoneme. Interacts with outer dynein arm (ODA) subunits.
Synonyms: C16orf71; DAAP1; FLJ43261; DKFZp686H2240
Tractability: No criterion of Open Targets' tractability assessment is met for any kind of drug.
Gene: Protein-coding gene on chromosome 16 (4,734,344 to 4,749,396, forward strand). Ensembl gene ENSG00000166246.
Subcellular location: Dynein axonemal particle; Cytoplasm
Gene Ontology:
Molecular function: dynein complex binding
Biological process: outer dynein arm assembly
Cellular component: cytoplasm; dynein axonemal particle
Genetic constraint (gnomAD): Loss-of-function variants: 57 observed, 48.83 expected, observed/expected ratio (o/e) 1.17, 90% interval 0.94 to 1.46. The upper end of that interval is the gene's LOEUF score, 1.46, which puts it in group 6 of 6, group 1 being the genes least tolerant of losing a copy. Missense variants: 831 observed, 660.81 expected, observed/expected ratio (o/e) 1.26, 90% interval 1.19 to 1.33. Synonymous variants: 318 observed, 271.2 expected, observed/expected ratio (o/e) 1.17, 90% interval 1.07 to 1.29.
Homologues: Orthologues: chimpanzee DNAAF8 (98% identical), macaque DNAAF8 (89% identical), rabbit DNAAF8 (63% identical), dog DNAAF8 (57% identical), pig DNAAF8 (52% identical), rat Dnaaf8 (49% identical), mouse Dnaaf8 (27% identical).
Diseases named in the same sentence as DNAAF8 in open-access papers:
DNAAF8 is named in the same sentence as 2 diseases in open-access papers, as found by Europe PMC text mining. Sharing a sentence is not in itself a finding about the gene and the disease.
DNAAF8 shares sentences with these, for which no sentence is quoted: infection (1 paper); leukemia (1).